CASC19 (cancer susceptibility 19)
Synonyms: CARLo-6; CARLO4; CARLo-4; PCA2; TCONS_00015167; PCAT2; formerly LINC01245
Gene: Long non-coding RNA gene on chromosome 8 (127,072,694 to 127,227,541, reverse strand). Ensembl gene ENSG00000254166.
Diseases named in the same sentence as CASC19 in open-access papers:
CASC19 is named in the same sentence as 37 diseases in open-access papers, as found by Europe PMC text mining. Sharing a sentence is not in itself a finding about the gene and the disease. The quoted sentences say what the papers report.
pancreatic cancer (7 papers, 2021 to 2025). "Nevertheless, the precise mechanisms underlying CASC19’s impact on pancreatic cancer progression remains to be elucidated." (PMID 41023804, 2025). "In-vitro loss and gain-of-function experiments showed that CASC19 is an oncogenic lncRNA promoting proliferation and metastasis of pancreatic cancer, while inhibiting apoptosis." (PMID 41023804, 2025). "In our current study, we have identified a lncRNA CASC19 which is notably upregulated in pancreatic tumor tissue and pancreatic cancer cell lines and is associated with advanced stages of the disease and poor patient survival." (PMID 41023804, 2025). "We have also found elevated CASC19 level was associated with more aggressive stages of pancreatic cancer, according to the web server GEPIA2." (PMID 41023804, 2025). "However, a reduced migration and invasion was seen in pancreatic cancer cell line with loss of expression of the CASC19." (PMID 41023804, 2025). "Outcome of MTT assay demonstrated that PSPC1 silencing could reverse the increased proliferation in pancreatic cancer cells caused by CASC19 overexpression." (PMID 41023804, 2025). "The lncRNA CASC19 is markedly upregulated and is associated with tumor progression and poorer prognoses in various cancers, including colorectal cancer, advanced gastric cancer, non-small lung cancer cells, and pancreatic cancer." (PMID 35685422, 2022). "Gene expression level of CASC19 was determined in several human pancreatic cancer cell lines (AsPc-1, BxPc-3, MIAPaCa-2, Panc-1 and CAPAN-2) and one normal human pancreatic ductal cell line (hTERT-HPNE) using qRT-PCR." (PMID 41023804, 2025). "Regarding the status of CASC19 in pancreatic cancer, there was only a single report delineating its role in pancreatic cancer through microRNA sponging, with no other detailed mechanisms known." (PMID 41023804, 2025). "Our findings elaborate the mechanism of CASC19 mediated tumorigenesis in pancreatic cancer, highlighting the role of PSPC1 in the process." (PMID 41023804, 2025). "The proliferation of pancreatic cancer cells was notably enhanced by CASC19 overexpression and reduced by downregulation of CASC19, as measured by MTT assay." (PMID 41023804, 2025). "Via successive rescue experiments, it was authenticated that the oncogenic functions of CASC19 in pancreatic cancer are mediated by regulating PSPC1 expression." (PMID 41023804, 2025). "Western-blot assay of the rescue experiment showed that upregulated PSPC1 protein level induced by CASC19 overexpression was abolished by PSPC1 siRNA in pancreatic cancer cell MIAPaCa-2." (PMID 41023804, 2025). "We have also found that high CASC19 expression promotes pancreatic cancer cell proliferation, cell cycle progression and metastatic ability of the cell with a reduction in apoptosis." (PMID 41023804, 2025). "The Kaplan–Meier overall survival (OS) analysis from GEPIA2 database depicted that pancreatic cancer patients with high CASC19 expression exhibited significantly poorer survival than the PDAC patients with low expression of CASC19." (PMID 41023804, 2025). "In this study, we aim to inquire about the oncogenic role of CASC19 in pancreatic cancer proliferation, migration, cell cycle and apoptosis." (PMID 41023804, 2025). "This was followed by some cellular assays to determine the oncogenic effect of CASC19 on pancreatic cancer progression." (PMID 41023804, 2025). "To delve deeper into the mechanisms of CASC19 in pancreatic cancer progression, we carried out a subcellular fractionation assay and found that CASC19 is present mainly in the nucleus of pancreatic cancer cells." (PMID 41023804, 2025). "Sense and antisense transcripts of CASC19 were transcribed in-vitro, biotinylated and incubated with nuclear lysate of pancreatic cancer cell MIAPaCa-2 and the pulled protein extracts were then subjected to mass-spectrometry." (PMID 41023804, 2025).
pancreatic cancer (continued). "To further confirm that CASC19-induced oncogenic functions are mediating by PSPC1 in pancreatic cancer, we performed a rescue experiment in CASC19 overexpressing cells with siRNA against PSPC1." (PMID 41023804, 2025). "CASC19 expression was found to be much higher in the pancreatic cancer cell lines than the normal pancreatic ductal cell line." (PMID 41023804, 2025). "Amongst these five pancreatic cancer cell lines, MIAPaCa-2 had the intermediate expression level of CASC19 and thus we chose the cell line for further investigations and cellular/functional assays." (PMID 41023804, 2025). "To summarize, our results imply that CASC19 is an oncogenic lncRNA that promotes tumor proliferation, cell cycle, EMT and metastasis in pancreatic cancer with a reduction in apoptosis and is linked to poor prognosis in pancreatic cancer." (PMID 41023804, 2025). "PSPC1 protein expression was also high in pancreatic cancer cell lines like that of CASC19 expression." (PMID 41023804, 2025). "This study identified CASC19 as a significantly overexpressed lncRNA with high oncogenic potential in pancreatic cancer, aiming to uncover its molecular mechanism in tumor progression." (PMID 41023804, 2025). "High CASC19 expression was found in pancreatic tumor tissues and multiple pancreatic cancer cell lines." (PMID 41023804, 2025). "Collectively, these findings suggest that elevated expression of CASC19 promote metastasis in pancreatic cancer cells." (PMID 41023804, 2025). "First, the expression of CASC19 was determined in separate set of 17 pairs of pancreatic tumor tissues and adjacent normal pancreatic tissues (collected from a separate cohort of patients with tumours of either TNM Stage-IB or Stage-II) by qRT-PCR." (PMID 41023804, 2025). "Thus, to find out the CASC19 regulated transcriptome, CASC19 was overexpressed and knocked down in pancreatic cancer cell line MIAPaCa-2 and subjected to RNA-sequencing." (PMID 41023804, 2025). "Thus, the positive correlation of CASC19 and PSPC1 expression and the CASC19/PSPC1/β-catenin axis seems to be a promising therapeutic target in pancreatic cancer treatment." (PMID 41023804, 2025). "Nuclear localization of the lncRNA CASC19 indicated that it might contribute towards progression of pancreatic cancer via transcriptional regulation of its target genes." (PMID 41023804, 2025). "Therefore, nuclear and cytoplasmic fractionation followed by qRT-PCR revealed the presence of CASC19 in the nuclear fraction of the pancreatic cancer cell MIAPaCa-2." (PMID 41023804, 2025). "Therefore, we conducted CHX assay, MG132 assay and ubiquitination assay which suggests that CASC19 increases PSPC1 protein stability by reducing its ubiquitin-proteasome mediated degradation in pancreatic cancer." (PMID 41023804, 2025). "Similarly, protein expression of Bcl-2 decreased and Bax increased when CASC19 was silenced in pancreatic cancer cell line MIAPaCa-2." (PMID 41023804, 2025). "CASC19 has been documented to be associated with the development and progression of a number of malignancies, including gastric cancer, glioma, and pancreatic cancer, but it has not been reported in HCC." (PMID 37535570, 2023). "The lncRNA CASC19 developed pancreatic cancer with CASC19/miR-148b/E2F7 axis." (PMID 35047414, 2021). "In pancreatic cancer (PC), CASC19 could facilitate malignant growth and metastasis of PC via miR-148b/E2F7 ceRNA axis with sponge activity." (PMID 34594376, 2021). "Hence, we wanted to investigate whether a similar mechanism is contributing to pancreatic cancer progression, as our findings, so far, showed that high CASC19 expression contributes to more PSPC1 protein stability and more PSPC1 availability in the nucleus." (PMID 41023804, 2025). "Accompanied with continued research, the novel CASC19/PSPC1/β-catenin axis holds promise as a potential and effective therapeutic target for advanced pancreatic cancer." (PMID 41023804, 2025).
pancreatic cancer (continued). "Hereby, we find that CASC19 enhances the PSPC1 protein stability and thus potentiates the PSPC1-mediated nuclear translocation of β-catenin to promote pancreatic cancer progression." (PMID 41023804, 2025). "Overall, these findings demonstrate that elevated expression of CASC19 contributes to EMT and metastasis in pancreatic cancer cells." (PMID 41023804, 2025). "Previous studies demonstrated that CASC19 was involved in clear cell renal cell carcinoma (ccRCC), non-small cell lung cancer (NSCLC), glioma, and pancreatic cancer." (PMID 36769373, 2023). "The result showed significantly high expression of CASC19 in pancreatic cancer patients as compared to the noncancerous part of pancreas." (PMID 41023804, 2025). "Therefore, it can be concluded that CASC19 expression did not exert any influence on PSPC1 protein synthesis, rather post-translationally regulate PSPC1 expression by affecting its ubiquitin-mediated degradation and enhance PSPC1 protein stability in pancreatic cancer." (PMID 41023804, 2025).
prostate carcinoma (7 papers, 2019 to 2025). A carcinoma that arises from epithelial cells of the prostate gland. "GWAS studies have showed that upregulation of the CASC19 gene containing the SNP rs138042437 greatly increases prostate cancer susceptibility." (PMID 31422382, 2019).
nasopharyngeal carcinoma (5 papers, 2021 to 2023). A carcinoma arising from the nasopharyngeal epithelium. "LncRNA CASC19 caused the radioresistance of nasopharyngeal cancer cells, which was reversed by miR-340-3p mimics." (PMID 37569824, 2023). "Radiation upregulates lncRNA CASC19 and downregulates miR-340-3p in nasopharyngeal cancer cells." (PMID 37569824, 2023). "Interestingly, CASC19 siRNA (siCASC19) was observed to inhibit autophagy and promote apoptosis in nasopharyngeal carcinoma." (PMID 37535570, 2023).
colon cancer (4 papers, 2022 to 2025). "We assessed the expression levels of CASC19 and LINC00460 genes in a pool of colon cell lines: DLD-1, COLO-205, HCT116, and LoVo as colon cancer models and CCD841 as a normal epithelial cell line." (PMID 38740871, 2024). "KLRL1-AS1 (ENSG00000245648) and CASC19 (ENSG00000254166), both down-regulated, exhibit atypical expression patterns in colon cancer, indicating significant roles in its pathology." (PMID 38909013, 2024).
non-small cell lung carcinoma (4 papers, 2022 to 2025). A group of at least three distinct histological types of lung cancer, including non-small cell squamous cell carcinoma, adenocarcinoma, and large cell carcinoma.
gastric cancer (3 papers, 2019 to 2025). A primary or metastatic malignant neoplasm involving the stomach. "In recent experiments, overexpression of CASC19 enhanced the invasive and migratory functions of colorectal and gastric cancer cells, while knockdown of CASC19 inhibited proliferation and migration in vitro." (PMID 37535570, 2023). "Furthermore, quantitative real-time PCR assay confirmed that CASC19 expression in four human gastric cancer cells (AGS, BGC-823, MGC-803, and HGC-27) was significantly upregulated compared with human normal gastric mucosal epithelial cell line (GES-1)." (PMID 31422382, 2019).
glioma (3 papers, 2022 to 2023). A benign or malignant brain and spinal cord tumor that arises from glial cells (astrocytes, oligodendrocytes, ependymal cells). "Some, SOX2-OT, ZFAS1, SAMMSON, CASC19/PCAT2, and PVT1, have already been associated with various cancers, including gliomas." (PMID 35852875, 2022).
liver cancer (3 papers, 2022 to 2025). An epithelial or non-epithelial malignant neoplasm that arises from the liver. "The results indicated that CASC19 was highly expressed in liver cancer tissues and that downregulation of CASC19 inhibited the proliferation, invasion and migration of Hep3B cells in vitro." (PMID 37535570, 2023). "CASC19 was highly expressed in HCC in the TCGA data, which was confirmed by qPCR results in 14 liver cancer tissues and paired para-carcinoma tissues (The average expression level: 3.945 to 1.000, P <0.05)." (PMID 37535570, 2023).
breast carcinoma (2 papers, 2021 to 2024). "The data show an upregulation of breast cancer related genes in T1 and C1 relative to 10A, including LRATD2, PCAT1, CASC19, CASC8, POU5F1B, PVT1 and MYC on chromosome 8." (PMID 38076897, 2024).
Clear Cell Renal Cell Carcinoma (2 papers, 2021 to 2023). "Evidence suggests that the overexpression of CASC19 in Clear Cell Renal Cell Carcinoma (ccRCC) might play an oncogenic role in cancer progression, and knockdown of CASC19 suppressed cell proliferation, migration, and invasion in nonsmall cell lung carcinoma (NSCLC)." (PMID 33573349, 2021).
osteoarthritis (2 papers, 2021 to 2023). A noninflammatory degenerative joint disease occurring chiefly in older persons, characterized by degeneration of the articular cartilage, hypertrophy of bone at the margins and changes in the synovial membrane. "It was concluded that lncRNA CASC19 accelerated chondrocytes apoptosis and proinflammatory cytokine production to exacerbate osteoarthritis development through regulating the miR-152-3p/DDX6 axis." (PMID 34158095, 2021). "Although our study highlighted a CASC19-regulated regulatory mechanism in osteoarthritis progression, it is still limited because of the small sample size." (PMID 34158095, 2021). "Moreover, CASC19 could accelerate chondrocyte apoptosis and proinflammatory cytokine production and exacerbate osteoarthritis development by regulating the miR-152-3p/DDX6 axis." (PMID 36769373, 2023).
head and neck squamous cell carcinoma (1 paper, 2021). A squamous cell carcinoma that arises from any of the following anatomic sites: lip and oral cavity, nasal cavity, paranasal sinuses, pharynx, larynx, and salivary glands. "According to the Kaplan–Meier overall survival (OS) analysis, the prognosis of patients with a high expression of CASC19 in head and neck squamous cell carcinoma (HNSC) was significantly worse than that of HNSC patients with a low expression of CASC19 (data from GEPIA database)." (PMID 33573349, 2021).
lymph node metastasis (1 paper, 2019). "CASC19 was upregulated in AGC clinical samples and was significantly associated with higher pathologic TNM stage, pathologic T stage, lymph node metastasis, and poor overall survival." (PMID 31422382, 2019).
cancer (25 papers, 2018 to 2025). A tumor composed of atypical neoplastic, often pleomorphic cells that invade other tissues. "CASC19 has been uncovered to be implicated in various cancers, but its function in OA remains indistinct." (PMID 34158095, 2021). "Cancer susceptibility 19 (CASC19) was the top hub lncRNA among the lncRNAs included in the gene module most significantly correlated with AGC’s pathological variables." (PMID 31422382, 2019). "To ensure the reliability of our results, we selected two lncRNAs from the 11 that show a specific expression in CRC samples for further validation: CASC19 (Cancer Susceptibility candidate 19; ENSG00000254166.2) and LINC00460 (long intergenic non-protein coding RNA 460; ENSG00000233532.5)." (PMID 38740871, 2024). "In addition, cancer susceptibility 2 (CASC2) and cancer susceptibility 19 (CASC19) have been demonstrated to exhibit proinflammatory and proapoptotic effects by regulating IL-17 and the miR-152-3p/DDX6 axis, respectively." (PMID 37189327, 2023). "Therefore, we assumed that CASC19, another lncRNA of the cancer susceptibility candidate (CASC) family, might also be involved in OA development." (PMID 34158095, 2021). "We carried out an in vitro preliminary experimental validation given the numerous functions of CASC19 in cancers." (PMID 37535570, 2023). "It has also been suggested that LINC02407 is closely related to CASC19 and cancer cell survival and affects GC via the LINC02407-miR-6845-5p/miR-4455/ADGRD1 pathway." (PMID 36928327, 2023). "CASC19, one of the recently identified lncRNA, has been demonstrated to participate in various cancers." (PMID 34158095, 2021). "Metastatic potential of a cancer cell is generally determined by the migratory and invasive properties of the cell, and we wanted to investigate whether changes in CASC19 expression could modulate the phenomenon." (PMID 41023804, 2025). "Moreover, elevated wound-healing, migration and invasion ability of cancer cells with CASC19 upregulation were significantly attenuated by PSPC1 siRNA in respect to control cells." (PMID 41023804, 2025). "The CASC19, AC090197.1, AC099850.3, AL033397.2, LINC00462, and B3GALT1-AS1were found to be upregulated in the high-risk group, indicating that all these markers were involved in the malignancy processes for KIRP sufferers and were cancer-promoting factors." (PMID 36104680, 2022). "Based on these findings, we hypothesis that CASC19, along with other lncRNAs in this chromosomal region, may also be critically involved in the progression of cancer." (PMID 31422382, 2019). "CASC19 has been investigated in various cancers, but its role in OA keeps unknown." (PMID 34158095, 2021). "CASC19, AC090197.1, AC099850.3, AL033397.2, LINC00462, and B3GALT1-AS1 were found to be significantly increased in the high-risk group, indicating that all of these markers implicates the malignancy processes for KIRP patients and may be cancer-promoting variables." (PMID 36104680, 2022). "Evidence showed that overexpressed CASC19 elevated the expressions of CEMIP and EMT biomarkers in CRC cells, which can be reversed by inducing the expression of miR-140-5p in cells; they were highly correlated with the poor cancer prognosis." (PMID 40746360, 2025). "Our findings reveal that inhibiting CASC19 expression significantly impedes cancer cell migration, whereas the knockdown of LINC00460 does not produce a similar effect." (PMID 38740871, 2024).